BRAF (B-Raf proto-oncogene, serine/threonine kinase)
Diseases named in the same sentence as BRAF in open-access papers (continued):
Sharing a sentence is not in itself a finding about the gene and the disease.
melanoma (continued). "reveal the relationship between the TME and drug tolerance in BRAF‐mutant melanoma treated with a BRAF inhibitor (BRAFi) through intravital imaging of cells via an ERK/MAPK biosensor: the inhibition of BRAF leads to paradoxical activation of CAFs and matrix remodeling." (PMID 37638338, 2023). "Accuracy and robustness might be enhanced when utilities calculated for patients with BRAF-mutant melanoma in patients with immunotherapy are available in the future." (PMID 36653848, 2023). "Evidence suggests that initiating treatment of BRAFmut melanoma with BRAF inhibitors." (PMID 37762086, 2023). "In the present study, we demonstrate a key role for TFEB in melanoma that is independent of BRAF mutation, which is a genetic trait that characterises ~52% of human melanomas." (PMID 37160873, 2023). "Moreover, BRAF‐mutant melanoma cells display initial response to BRAFi treatment, but they gain tolerance to BRAFi quickly after contacting with stromal cells." (PMID 37638338, 2023). "BRAF mutant melanoma is known to respond to TT in three phases." (PMID 36967556, 2023). "Moreover, increased CRAF levels have been reported to facilitate resistance in BRAF mutant melanomas." (PMID 38111008, 2023). "Here, we investigated and compared the molecular profile of BRAF and NRAS mutated and wildtype melanoma patients’ tissue samples using imaging mass spectrometry-based proteomic technology, to identify specific molecular signatures associated with the respective tumors." (PMID 36982192, 2023). "However, in our study, CYTL1 was a pro-oncogenic factor in melanoma, and in melanoma patients, its elevated expression was linked to a shorter OS and DFS., especially those with BRAF mutations." (PMID 37745303, 2023). "Moreover, in melanoma, BRAF mutations are linked to a high expression of EZH2, which is associated with melanoma progression, worse patient survival, and resistance to MAPK inhibitors." (PMID 37510333, 2023). "In contrast to this, we observed synergistic effects of the combined inhibition of BRAF and EZH2 only on melanoma cells resistant to vemurafenib, whereas in susceptible melanoma cells, we observed no additional benefit compared to treatment with vemurafenib alone." (PMID 36768289, 2023). "Moreover, in the CheckMate 067 trial, a clinical benefit was observed numerically with nivolumab plus ipilimumab versus nivolumab alone in the general patient population, with increased benefit in patients with BRAF-mutant melanoma." (PMID 37507765, 2023). "In addition, the possibility to stratify patients with BRAF-mut melanomas for a longer benefit of the therapy with BRAFi and MEKi is challenging and warrants of further validation in an enlarged cohort of patients." (PMID 38008717, 2023). "Besides immunotherapy, small molecule inhibitors selectively targeting the BRAF kinase such as vemurafenib, dabrafenib, and encorafenib have been successful in treating BRAF mutant melanoma." (PMID 36251678, 2023). "In concordance with this, BRAF-mutant CRC cell lines express higher levels of EGFR than BRAF-mutant melanoma cell lines, which may explain the difference in the efficacy of BRAF inhibitors in the clinical setting among cancer types." (PMID 36900187, 2023). "USP14 participates in the resistance to BRAF inhibitors in melanoma cells." (PMID 36694209, 2023). "Analysis showed that mutations in BRAF were significantly associated with melanoma subtypes while N-RAS mutations did not exhibit any statistically significant association with the four types of melanomas." (PMID 37217528, 2023). "Note that vemurafenib, another mutant BRAF inhibitor commonly used to treat melanoma, would be modeled identically to dabrafenib; in this analysis, these drugs could be used interchangeably." (PMID 37043573, 2023). "The BRAF V600K mutation, which is seen in 5-10% of all sequenced melanoma genomes, is caused by a non-dipyrimidine AC > TT substitution." (PMID 37142570, 2023).
melanoma (continued). "In addition, another study showed that activation of the MAPK signaling pathway is critical for cancer-immune evasion in BRAF-mutant melanoma cells." (PMID 37205993, 2023). "BRAF inhibition promotes cancer cell-autonomous mechanisms of ECM production and pro-fibrotic features in these xenograft models of melanoma therapeutic responses associated with ECM reprogramming, accumulation of collagen fibers and tumor stiffening in TT-treated mice." (PMID 36774337, 2023). "Inhibition of this signaling pathway resensitizes melanoma to BRAF inhibitors, suggesting that therapeutic strategies that target stromal–tumor interactions may have the potential to overcome drug resistance." (PMID 37638338, 2023). "Therefore, the current study is aimed at stratifying IRGs to evaluate prognosis and immunotherapy response in patients with BRAF V600E WT and BRAF V600E-mutant melanoma." (PMID 36704723, 2023). "Although adjuvant therapies with immune checkpoint inhibitors (ICI) and BRAF/MEK inhibitors improve recurrence-free survival (RFS) in stage III melanoma patients significantly, prognostic factors are needed to identify patients with a high risk of disease recurrence." (PMID 36765660, 2023). "Although immunotherapy dramatically enhances health outcomes in patients with BRAF-mutant melanoma, the optimal combination of immune-based treatments is still unknown from a value standpoint." (PMID 36653848, 2023). "For BRAF-mutant advanced melanoma, the vemurafenib-cobimetinib strategy could be considered the most cost-effective treatment at the willingness-to-pay threshold of $150,000." (PMID 36653848, 2023). "Furthermore, specific mutations in the TERT promoter have been found to frequently coexist with BRAF V600E variation in melanoma and observed to affect the disease-free survival of cancer patients." (PMID 38033865, 2023). "Melanomas that develop on non-sun-exposed anatomical sites are associated mostly with BRAF V600E mutations, which are considered one of the key factors to nevogenesis (formation of common nevi)." (PMID 36676131, 2023). "It has been suspected that the sequence of targeted therapy and immunotherapy may be an important determinant of long-term responses and survival in BRAF mutant melanoma patients." (PMID 37444637, 2023). "Cytokines activate ITCH to maintain BRAF activity and promote the tumorigenicity of melanoma cells." (PMID 36694209, 2023). "Furthermore, pharmacological inhibition was tested in tumors developed from cell lines obtained from a genetically engineered melanoma model that reflects human triple wild-type (BRAF/RAF/NF1-WT) melanoma and its response to immunotherapy." (PMID 37712416, 2023). "Indeed, preliminary analysis of BRAFV600E melanoma biopsies revealed that CREB phosphorylation decreases upon BRAF inhibition but is restored in relapsing tumors." (PMID 37834284, 2023). "Similarly, lung and melanoma patient-derived xenografts treated with inhibitors of the MAPK signalling pathway developed amplifications of the BRAF gene, which allowed the bypass of the targeted oncogene inhibition." (PMID 37721639, 2023). "Thus, AR gene expression is consistently induced in BRAFi-resistant melanoma cells as well as in naïve melanoma cells upon acute exposure to BRAF/MEK inhibitors, involving AR nuclear translocation and a positive feedback loop." (PMID 37838724, 2023). "This study suggests that combining AMPK activators, such as Phenformin, with BRAF inhibitors may offer significant therapeutic advantages in melanoma treatment." (PMID 38105263, 2023). "For instance, in melanoma, BRAF KDD exons 10–18 conferred resistance to BRAF inhibitor treatment." (PMID 36325957, 2023). "We compared our candidate drugs to known anti-melanoma and NO-based drugs using publicly available drugs screens and high-throughput CRISPR data and experimentally validated six of these candidates in BRAF and NRAS mutated cell lines in mono and combination treatment with BRAF/MEK inhibitors." (PMID 37495601, 2023).
melanoma (continued). "COMBI-AD is a phase three randomized controlled trial that randomized 870 patients with BRAF-mutant resected stage III melanoma (with lymph node metastases > 1 mm for stage IIIA) to receive the combination of BRAF inhibitor dabrafenib 150 mg bid and MEK inhibitor trametinib 2 mg daily vs. placebo." (PMID 36836846, 2023). "The interim data presented in the AVAST-M trial suggested that BRAF mutant melanomas may be selectively sensitive to bevacizumab." (PMID 36539575, 2023). "Ulixertinib and Pevonedistat may synergize with BRAF-targeted inhibitors to produce an anti-malignant proliferation of melanoma cells." (PMID 37770477, 2023). "Our recent in vitro study unveiled a promising approach in which the BRAF inhibitor encorafenib, although being a V600E/K-specific inhibitor, had synergistic effects when combined with binimetinib in NRAS-mutated melanoma cells in terms of increased viability reduction and apoptosis induction." (PMID 38067230, 2023). "A dabrafenib and trametinib combination (hereafter D/T combination) significantly improved response rates (76% vs. 54%), prolonged progression-free survival (PFS; 9.4 versus 5.8 months), and reduced skin toxicities compared with dabrafenib monotherapy in BRAF melanoma patients." (PMID 37834284, 2023). "In this paper we provide compelling evidence that LNPs encapsulating selected oncosuppressor miRNAs such as miR-204-5p and miR-199b-5p may be considered as new tools to improve efficacy of current therapies for BRAF mutant melanoma." (PMID 36418472, 2023). "As these melanomas more frequently harbor BRAFV600E mutation, treatments with BRAF-targeted small molecules may also offer advantages (potentially in the adjuvant or advanced stages)." (PMID 36834954, 2023). "BRAF (B-Raf), a serine/threonine kinase in the MAPK signaling pathway, rarely shows activating mutations in breast cancer but is more common in other malignancies such as melanoma." (PMID 37885828, 2023). "Vemurafenib was the first to show efficacy in BRAF-mutant melanoma followed by dabrafenib." (PMID 37959729, 2023). "Coupled with the findings that BRAF inhibitors might induce ER stress in NRAS-mutant melanoma, leading to an amplification of MEK inhibitor activity, the combination of binimetinib and encorafenib might shift the balance towards better responses." (PMID 38067230, 2023). "Targeting the mechanical phenotype displayed by aggressive dedifferentiated mesenchymal-like BRAF-mutant melanoma cells and the fibrotic-like features of melanoma tumor microenvironment in combination with current TT and ICB clearly opens promising therapeutic avenues." (PMID 36774337, 2023). "Fusion genes in solid tumors may also occur, but in the case of melanoma these are very rare, affecting BRAF, ROS1, RET or NTRK." (PMID 36980598, 2023). "Similarly, upregulation of NRG1 and HER3 expression was found to induce resistance to anaplastic lymphoma kinase (ALK) and BRAF inhibitors in melanoma and thyroid cancer." (PMID 37947595, 2023). "A study investigated the effectiveness of combining recombinant methioninase (rMETase), which targets methionine dependence in cancer cells, with a first-line melanoma drug temozolomide (TEM) in a patient-derived orthotopic xenograft (PDOX) mouse model of BRAF V600E mutant melanoma." (PMID 37892558, 2023). "In this study, MITF-low zebrafish melanoma cells had striking transcriptional similarities to invasive melanoma signatures found in humans following treatment with small molecule inhibitors of MEK or BRAF." (PMID 37021774, 2023).
melanoma (continued). "Treatment of a panel of primary and established human melanoma cells with multistep increases of the BRAF inhibitor Dabrafenib (DAB), utilizing similar concentrations as in previous studies, resulted in the emergence of cells with greater capability to proliferate in the presence of this compound." (PMID 37838724, 2023). "Furthermore, a phase I trial study has demonstrated the potential synergy between anti-PD-1 inhibitor and other BRAF/MEK inhibitors in treating patients with BRAF-mutant stage IIIC-IV melanoma (NCT03543969)." (PMID 38105263, 2023). "PAK1 inhibition results in the sensitization of BRAF-mutant melanoma to a BRAF inhibitor." (PMID 36830998, 2023). "Data from the BRAF wild-type arm of our study will also be useful to understand whether MEK inhibitors have immune-stimulating or immune-suppressor effect in advanced melanoma." (PMID 36845751, 2023). "To date, standard treatment for patients with macroscopic stage III melanoma includes surgery followed by adjuvant immune checkpoint blockade (ICB) directed against programmed death-1 (anti-PD-1) or adjuvant BRAF/MEK-targeted therapy for those with BRAF-mutant melanoma." (PMID 36920329, 2023). "Moreover, clinical trials in BRAFV600E melanoma demonstrated promising efficacy and long-lasting antitumor responses with the combined inhibition of BRAF/MEK and PD-1/PD-L1 pathways." (PMID 36702949, 2023). "This indicates a similar prevalence of the BRAF gene in both upper and lower trunk melanoma." (PMID 37685328, 2023). "The hypothesis of the priming of BRAF V600 mutant melanoma through prior immunotherapy was recently backed mechanistically by in vivo data." (PMID 37760406, 2023). "From the TCGA database, mutations of BRAF and RAS mainly exist in melanoma and CRC." (PMID 36872366, 2023). "Furthermore, we test oncogene-targeted TKIs with EGFR, HER2, and BRAF inhibitors using EGFR-mutant (EGFR+) NSCLC, HER2-amplified (HER2+) breast cancer (BC), and BRAF-mutant (BRAF+) melanoma cells." (PMID 37880373, 2023). "In this context, we have recently reported that miRNA-based therapy may be a successful strategy to improve MAPKi efficacy in BRAF-mutant melanoma both in vitro and in vivo." (PMID 38008717, 2023). "In addition, we showed that the combination of these PHB ligands with the BRAF inhibitor Dabrafenib overcame innate resistance in a BRAF mutant melanoma line (MM029), while it was less pronounced in a BRAFi-sensitive line (MM074)." (PMID 37508519, 2023). "The responsiveness of NRAS-driven melanomas to targeted therapies is even worse, as BRAF inhibitors are generally inapplicable in this scenario, while MEK inhibitors alone do not offer significant improvements over conventional chemotherapy in the overall survival or the safety profiles." (PMID 37830586, 2023). "HPF can block STAT3 tyrosine phosphorylation in all the BRAF-mutated melanoma cell lines after 24 h treatment without affecting the total STAT3 protein level." (PMID 36674794, 2023). "Of particular interest was the concomitant upregulation of the dual specificity phosphatases 4 and 6 (DUSP4 and 6), whose inactivation has recently emerged as digenic synthetic lethal targets in NRAS and BRAF mutant melanoma cell lines acting through ERK hyperactivation." (PMID 37946160, 2023). "More importantly, the levels of SEMA6A were also higher in drug-resistant and BRAF-mutant melanoma." (PMID 38067240, 2023).
melanoma (continued). "In contrast, in non-melanoma cell lines with BRAF mutation, DUSP4 silencing did not affect their growth (a glioma cell line and a colorectal cancer cell line)." (PMID 37946160, 2023). "Moreover, combined BRAF and MEK inhibitors have been approved by the US Food and Drug Administration (FDA) to treat melanoma patients with V600E/K mutation in the BRAF gene." (PMID 37627547, 2023). "Mucosal melanoma frequently harbors atypical BRAF mutations other than the p.V600 hot spot (such as p.G469A, p.L597Q, p.N581S, p.T599I, and p.G596R), rendering BRAF inhibitors that revolutionized melanoma treatment not applicable in this population." (PMID 37239381, 2023). "In this study, the frequency of BRAF mutation was similar in melanoma (63%) and nevi (65.2%) and the BRAF/NRAS transformed nevi did not have a higher chance of being associated with melanoma than a wild type of nevi." (PMID 36676131, 2023). "The category of melanomas with “little or no UV/CSD exposure” rarely harbor BRAF, NRAS, or NF1 mutations." (PMID 37174072, 2023). "The researchers suggested that combining miR-34a with targeted therapy could be a promising strategy to enhance the efficacy of targeted therapies in BRAF-mutant melanoma." (PMID 37504268, 2023). "However, after 4 years, two lesions, one in the lung and one in the right arm, were excised and confirmed as melanoma recurrence (BRAF wild type)." (PMID 38132400, 2023). "Additionally, in patients with advanced BRAF wild-type melanoma, the concomitance of basal elevated lactate dehydrogenase (LDH) and NLR increasing on treatment with ICIs has been associated with reduced progression-free survival (PFS)." (PMID 37684649, 2023). "Response rate was dependent on BRAF genotype, with the best treatment response seen in non-E/K V600-mutated melanomas when given BRAF plus MEK inhibitors (ORR 56%, median PFS 8.0 months)." (PMID 37370834, 2023). "BRAF alteration were most observed in melanoma and colorectal cancer." (PMID 36910668, 2023). "Moreover, combination treatment of tunlametinib with vemurafenib resulted in remarkable tumor inhibition in BRAF mutant melanoma cells, which indicates a strong synergistic effect (Q = 1.51, p < 0.05)." (PMID 37808191, 2023). "Melanoma cells isolated from a single BRAF+ patient were treated with vemurafenib and 1,25(OH)2D3." (PMID 37175742, 2023). "Moreover, it has been shown that during BRAF inhibitor treatment melanoma cells can lose MITF expression and de‐differentiate, marking the transition to an invasive subpopulation of treatment‐resistant cells." (PMID 36251678, 2023). "It has recently been demonstrated that inhibition of the transcription factor FOXP2 may increase sensitivity to vemurafenib in BRAF V600E melanomas, suggesting a potential future therapy strategy." (PMID 36979496, 2023). "For the primary melanoma cell line—WM3211 (VGP), with a wild type for BRAF, PTEN, N-RAS, and CDK4, and with a mutation at position 576 in the c-KIT gene, caspase 3 activation compared to the control was several times lower than for the metastatic lines Mel-1359 and MEWO." (PMID 37097377, 2023). "In contrast to the excellent outcomes in melanoma, single-agent BRAF inhibitors showed little to no clinical activity in patients with BRAF-V600E-mutated mCRC." (PMID 37627048, 2023). "Initial studies evaluated whether vemurafenib/dabrafenib induced the autophagic machinery in patient samples with BRAF-mutant melanoma by staining for the autophagy marker, LC3II." (PMID 37834222, 2023). "The mutations in BRAF V600, NRAS Q61, and c-KIT occur early in melanoma development." (PMID 38003476, 2023). "Also, after the depletion of SAMMSON, the sensitivity of mutant BRAF melanoma cells to vemurafenib increased, and the rate of apoptosis cells via induction of cleavage of caspase‐3 and caspase‐9 was promoted." (PMID 37772815, 2023).